IL1RAP (interleukin 1 receptor accessory protein)
Diseases named in the same sentence as IL1RAP in open-access papers (continued):
Sharing a sentence is not in itself a finding about the gene and the disease.
cervical cancer (4 papers, 2020 to 2025). A primary or metastatic malignant neoplasm involving the cervix. "Evidence also shows the association of cervical cancer and the aberrant alternative splicing of the IL1RAP gene." (PMID 33498485, 2021). "Studies revealed that the splicing factor SRSF10 can mediate AS of IL1RAP to facilitate oncogenesis in cervical cancer." (PMID 32528230, 2020). "As a splicing factor, SRSF10 mediates IL1RAP’s alternative splicing and promotes oncogenesis in cervical cancer." (PMID 32600379, 2020). "Therefore, aberrant alternative splicing of IL1RAP gene promotes immune evasion and promotes cervical cancer." (PMID 33498485, 2021).
gastric cancer (4 papers, 2022 to 2025). A primary or metastatic malignant neoplasm involving the stomach. "Multiple immune infiltration assays were conducted to investigate the association between IL1RAP and immune cells in gastric cancer." (PMID 40444099, 2025). "Since the inhibition of cytokine–cytokine receptor pathway may specifically associate with silencing of IL1RAP, in stomach cancer cells, the enrichment of CCRI associated genes was used to construct enrichment plots." (PMID 35488454, 2022). "A collection of 410 gastric cancer tissue samples was divided into two groups—those with high IL1RAP expression and those with low IL1RAP expression." (PMID 40444099, 2025). "IL1RAP plays a critical role in the tumor microenvironment of gastric cancer and serves as a robust predictor of immunotherapy efficacy in patients." (PMID 40444099, 2025). "IL1RAP plays a critical role in the tumor microenvironment of gastric cancer and serves as a robust predictor of immunotherapy efficacy in gastric cancer." (PMID 40444099, 2025). "After machine learning screening and independent dataset validation, high IL1RAP expression was identified as a poor prognostic factor for gastric cancer patients." (PMID 40444099, 2025). "In this study, we assessed the potential of IL1RAP as a novel therapeutic target in gastric cancer using machine learning algorithms and immunocorrelation analysis of single-cell data." (PMID 40444099, 2025). "Our findings were further validated by confirming elevated IL1RAP expression levels in gastric cancer tissues." (PMID 40444099, 2025). "The results demonstrated that both the mRNA and protein levels of IL1RAP were significantly upregulated in gastric cancer tissues." (PMID 40444099, 2025). "Our study revealed that IL1RAP expression is significantly elevated in gastric cancer at both protein and mRNA levels, which correlates with a poorer prognosis in patients." (PMID 40444099, 2025). "Secondly, further exploration is needed to fully understand the mechanisms by which IL1RAP is involved in gastric cancer." (PMID 40444099, 2025). "Univariate and multivariate Cox regression analyses revealed that IL1RAP serves as an independent prognostic marker for gastric cancer." (PMID 40444099, 2025). "We found a similar group of genes differentially expressed in both stomach cancer cell lines, indicating a presumptive functional role of IL1RAP in cancer progression." (PMID 35488454, 2022). "To investigate the potential clinical use of the IL1RAP expression profile, we analysed the transcriptomes of two stomach cancer cell lines (BCG‐823 and HGC‐27)." (PMID 35488454, 2022). "The siRNAs‐mediated knockdown of IL1RAP resulted in a substantial reduction in gastric cancer cell proliferation." (PMID 35488454, 2022). "We further optimized the IL1RAP siRNAs in vitro utilizing gastric cancer cells lines, enabling its use for further experiments." (PMID 35488454, 2022). "The identification and potential preclinical significance of secretory and membrane proteins, including the novel function and mechanistic roles of IL1RAP in the context of gastric cancer pathogenesis are described here." (PMID 35488454, 2022). "The significance of the human secretome and membrane proteome is elucidated by these findings, which indicate IL1RAP as a potential candidate biomarker for cytokine‐mediated cancer immunotherapy in gastric carcinoma." (PMID 35488454, 2022). "In vitro and in vivo data have indicated that IL1RAP knockdown significantly increased inflammation of tumor microenvironment-related inflammatory factors and suppressed the development of stomach carcinoma." (PMID 36685967, 2022). "We conducted an in-depth analysis of the role of IL1RAP within the gastric cancer microenvironment." (PMID 40444099, 2025). "Finally, the therapeutic efficacy of IL1RAP knockdown on gastric cancer should be confirmed through animal studies." (PMID 40444099, 2025).
gastric cancer (continued). "Therefore, IL1RAP is anticipated to be a promising target for enhancing gastric cancer immunotherapy." (PMID 40444099, 2025). "Investigating the pivotal role of IL1RAP in the tumor microenvironment of gastric cancer." (PMID 40444099, 2025). "We then examined whether gastric cancer cells rely on IL1RAP expression levels for proliferation, to indicate if IL1RAP has a functional role in cancer cell progression." (PMID 35488454, 2022). "However, current research on IL1RAP in gastric cancer remains limited." (PMID 40444099, 2025). "Firstly, the effect of IL1RAP on macrophage differentiation in gastric cancer has not been validated at the animal level." (PMID 40444099, 2025).
glioma (4 papers, 2021 to 2025). A benign or malignant brain and spinal cord tumor that arises from glial cells (astrocytes, oligodendrocytes, ependymal cells). "Furthermore, it is known that IL-1RAP is implicated in synaptic differentiation and neuronal growth, which could explain its implication in glioma proliferation." (PMID 36499246, 2022). "IL-1RAP was found overexpressed in vitro by western blotting in two glioma cell lines, M059 J and U373." (PMID 36499246, 2022). "In the presence of the protein tyrosine phosphatase receptors-δ (PTPRD), the interleukin-1 receptor accessory protein (IL1RAP) mediates, for example, the invasion of glioma cells by supporting the development of neuronal synapses and differentiation of neurons, in vitro." (PMID 34687436, 2022). "This study focused on the impact of protein tyrosine phosphatase receptor-δ (PTPRD) in glioma cells, and it was demonstrated that overexpression of PTPRD induces the upregulation of IL-1RAP." (PMID 36499246, 2022). "Moreover, under upregulation of PTPRD, an increase in the S and G2 cell cycle phases was observed in glioma cells, demonstrating that PTPRD, possibly through the IL-1RAP pathway, promoted the replication of glioma cells and so the proliferation of the tumor." (PMID 36499246, 2022).
chronic myeloid leukemia (3 papers, 2020 to 2025). "Single-cell gene expression preceded by genome-wide transcriptional analysis of AML and chronic myeloid leukemia (CML) LSCs have highlighted several cell markers, such as IL1RAP and CD25 that are overexpressed." (PMID 33363031, 2020). "Notably, in chronic myeloid leukemia, a unique surface expression profile has been identified in LSCs, characterized by consistent expression of markers such as CD25+, CD26+, CD56+, and IL-1RAP+." (PMID 40076750, 2025).
cognitive decline (3 papers, 2019 to 2025). "The aim of this study was to examine previously implicated genetic markers in and near IL1RAP in relation to AD risk, CSF tau and Aβ biomarkers, as well as cognitive decline, in a case (AD)-control study and an age homogenous population-based cohort." (PMID 30792413, 2019). "Similarly, IL1RAP genetic variants correlate with accelerated amyloid accumulation, elevated cerebrospinal fluid (CSF) tau, and cognitive decline in AD cohorts, further implicating inflammatory pathways in disease progression." (PMID 40656638, 2025). "In addition, for investigating cognitive decline, and especially AD risk, the samples used in this study are small compared to previous studies reporting associations with IL1RAP-related SNPs." (PMID 30792413, 2019). "The aim of this study was to examine the association of previously implicated genetic markers in and near IL1RAP in relation to AD risk, CSF tau and Aβ biomarkers, as well as cognitive decline over time, in a case (AD)-control study and an age homogenous representative population-based cohort." (PMID 30792413, 2019). "There were also associations found between the most significant SNP in IL1RAP and progression from MCI to AD, cognitive decline, temporal cortex atrophy and microglial activity." (PMID 39231932, 2024). "In addition, sub-analyses showed associations between the most significant IL1RAP SNP and progression from MCI to AD, longitudinal temporal cortex atrophy on MRI, cognitive decline, and microglial activity on PET." (PMID 30792413, 2019).
diabetes (3 papers, 2023 to 2024). "Studies targeting IL-1 therapies have shown a beneficial effect of anti–IL-1 therapy in T2D, but understanding of the direct effect of IL1RAP on diabetes is not clear." (PMID 39589852, 2024).
myeloid malignancies (3 papers, 2018 to 2022). "Given the importance of IL-1 and IL-33 in the development of myeloid neoplasms and the expression of IL1RAP on LSCs, targeting this receptor by mAbs is a promising strategy." (PMID 29868474, 2018).
psoriasis (3 papers, 2021 to 2025). An autoimmune condition characterized by red, well-delineated plaques with silvery scales that are usually on the extensor surfaces and scalp. "Two IL1RAP-targeting drugs, SPESOLIMAB and IMSIDOLIMAB, have already received regulatory approval for the treatment of inflammatory conditions such as psoriasis, ichthyosis, and Crohn’s disease." (PMID 41283645, 2025).
Salmonella Infections (3 papers, 2008 to 2021). Infections with bacteria of the genus SALMONELLA. "Since Il-1β signalling is important for control of Salmonella infection in the intestine and Il1rap is necessary for formation of a functional Il1 receptor, we intend to assess the physiological effect of SteD on Il1rap in future studies." (PMID 34314469, 2021).
dermatitis (2 papers, 2011 to 2014). An inflammatory process affecting the skin. "A role for IL33 in the dermatitis in SHARPIN-deficient mice is supported by the attenuation of inflammation in Sharpincpdm mice in which IL1RAP was deleted." (PMID 24465642, 2014). "The most recent study identified IL1 signaling was activated in the Sharpincpdm skin, and blockade of IL1 signaling by knockout of IL1RAP can significantly alleviate the dermatitis severity." (PMID 21660243, 2011).
glioblastoma (2 papers, 2024 to 2025). The most malignant astrocytic tumor (WHO grade IV). "In glioblastoma, IL1RAP, which is highly expressed in glioblastoma stem cells, sustains self-renewal and tumourigenic potential through the activation of Wnt/β-catenin and Notch signalling pathways." (PMID 40444099, 2025).
melanoma (2 papers, 2017 to 2025). A malignant, usually aggressive tumor composed of atypical, neoplastic melanocytes. "Twelve screening biopsies (six patients with HNSCC, five with NSCLC, one with melanoma) were used to evaluate target expression of IL1RAP and PD-L1 using immunohistochemistry." (PMID 40310569, 2025).
myeloid leukemia (2 papers, 2023 to 2024). A clonal proliferation of myeloid cells and their precursors in the bone marrow, peripheral blood, and spleen. "IL-1RAP is a transmembrane protein that potentiates multiple inflammatory signaling pathways, including IL-1, IL-33, IL-36G, and stem cell factor, and it has the unique feature of being expressed at higher levels in stem and progenitor cells from myeloid leukemia patients compared to normal HSPCs." (PMID 37498674, 2023).
myeloid sarcoma (2 papers, 2018 to 2021). A tumor mass composed of myeloblasts or immature myeloid cells. "Such myeloid sarcomas have been reported in MA9Ras xenografts expressing KMT2A-MLLT3 fusion protein, limiting the survival efficacy of the IL1RAP antibody, which otherwise showed strong anti-leukemic effect in the bone marrow." (PMID 34885074, 2021).
preeclampsia (2 papers, 2019 to 2024). Preeclampsia is a hypertensive disorder of pregnancy that is characterized by new-onset hypertension with proteinuria presenting after 20 weeks of gestation, and depending on mild or severe forms may initially present with severe headache, visual disturbances, and hyperreflexia. "Currently, IL1RAP is believed to be involved in the pathogenesis of preeclampsia by inhibiting trophoblast proliferation, migration, invasion, and angiogenesis." (PMID 39148025, 2024). "In summary, except for a few studies on the role of IL1RAP in trophoblast, the role of the other four genes in the pathogenesis of preeclampsia is still worth further investigation." (PMID 39148025, 2024). "Furthermore, the expression of IL1RAP in placental tissues of preeclampsia patients was found to be decreased." (PMID 39148025, 2024). "This study, through the analysis of a placental dataset, identified inflammation-related genes such as CXCR6, PIK3CB, IL1RAP, and OSMR coexisting in early-onset and full-term preeclampsia." (PMID 39148025, 2024).
Sepsis (2 papers, 2023 to 2025). Sepsis is defined as life-threatening organ dysfunction caused by a dysregulated host response to infection. "In addition, the immune response mediator of IL-18 and proinflammatory mediator of IL-1 receptor accessory protein (IL1RAP) were sharply increased in the induced group, which was closely associated with sepsis severity in patients." (PMID 40238755, 2025).
stomach adenocarcinoma (2 papers, 2022 to 2025). "IL1RAP is a promising cell‐surface marker and has been found to be significantly upregulated in gastric adenocarcinomas compared with normal adjacent tissue." (PMID 35488454, 2022). "IL1RAP expression is significantly increased in each successive stage of stomach adenocarcinomas compared with adjacent non‐malignant tissue." (PMID 35488454, 2022).
AIDS (1 paper, 2022). A syndrome resulting from the acquired deficiency of cellular immunity caused by the human immunodeficiency virus (HIV). "Our current study also reported the upregulation of IL1RAP in AIDS-KS tissues when compared to those normal skin tissues." (PMID 36457850, 2022).
Allergy (1 paper, 2020). An allergy is an immune response or reaction to substances that are usually not harmful. "C2, C9, IL5, SIGLEC15, and IL1RAP are examples of molecules with roles in immunity, inflammation and allergy that demonstrate seasonal effects." (PMID 33004787, 2020). "SIGLEC15 and IL1RAP peak in late spring/early summer, consistent with their role in allergies which often peaks in spring and early summer, and IP10, C2 and C6 peak in late fall/winter consistent with their role in fighting infections which often occur during the late fall/winter." (PMID 33004787, 2020).
atherosclerosis (1 paper, 2024). A disease characterized by the build-up of fatty material and calcium deposition in the arterial wall resulting in partial or complete occlusion of the arterial lumen. "In atherosclerosis, the role of IL-1β has been thoroughly studied, but there is evidence that other IL1RAP-related cytokines are implicated in disease progression." (PMID 38563353, 2024). "To test this hypothesis and investigate the role of IL1RAP in atherosclerosis, we treated apolipoprotein E–deficient (Apoe−/−) mice with a non-depleting IL1RAP-blocking antibody." (PMID 38563353, 2024). "Using a novel anti-IL1RAP-blocking antibody, we investigated the role of IL1RAP in atherosclerosis." (PMID 38563353, 2024). "Flow cytometric analysis revealed high levels of IL1RAP on CD11b+CD14+ macrophages, suggesting that this population may be a key target for IL1RAP blockade in atherosclerosis." (PMID 38563353, 2024). "Given the evidence from the canakinumab trial, we propose that the reduced plaque burden observed after IL1RAP blockade is at least in part mediated by limiting IL-1 signalling but that IL-33 and IL-36 signalling may also act to aggravate atherosclerosis by promoting chemokine release." (PMID 38563353, 2024). "Collectively, these results demonstrate that IL1RAP blockade may regulate chemokine production of both haematopoietic and non-haematopoietic cells, with implications for leucocyte recruitment and the development of atherosclerosis." (PMID 38563353, 2024). "To evaluate the effect of IL1RAP on the development of atherosclerosis, we administered a blocking non-depleting (LALA-PG modified) anti-IL1RAP antibody or isotype control IgG to Apoe−/− mice." (PMID 38563353, 2024).
biliary atresia (1 paper, 2013). A rare, biliary tract disease characterized by progressive obliterative cholangiopathy of the intra- and extrahepatic bile ducts, occurring in the embryonic/ perinatal period, leading to severe and persistent neonatal jaundice and acholic stool. "For biliary atresia, a recent report identified miR-29a to be increased in the livers of neonatal mice subjected to a similar RRV infection protocol, and to target the Igf1 and Il1rap genes in vivo." (PMID 24138927, 2013).
epilepsy (1 paper, 2025). A brain disorder characterized by episodes of abnormally increased neuronal discharge resulting in transient episodes of sensory or motor neurological dysfunction, or psychic dysfunction. "We identified three methylation biomarkers (IL1RAP, HIPK2 and CNMD) and validated their utility in differentiating FCD IIa from IIb in a larger replication study and an independent cohort of patients with epilepsy." (PMID 40860011, 2025).
gastric tumours (1 paper, 2022). "We measured the association between IL1RAP and the average fraction of individual immune cell types for each TCGA gastric tumour." (PMID 35488454, 2022). "Furthermore, the CCRI biomarker candidates for gastric tumours, reported herein, particularly IL1RAP, are likely to help in the development of less invasive and more accurate diagnostic and potentially therapeutic modality." (PMID 35488454, 2022). "The gastric tumours had a negative correlation between IL1RAP and the fraction of T‐cell populations and B‐cell populations." (PMID 35488454, 2022).
hypercholesterolaemia (1 paper, 2024). "Analysis of wild-type mice demonstrated similar patterns of IL1RAP expression, suggesting that the levels of IL1RAP expression on these cells are not contingent on hypercholesterolaemia." (PMID 38563353, 2024).
Insulin resistance (1 paper, 2022). Increased resistance towards insulin, that is, diminished effectiveness of insulin in reducing blood glucose levels. "Subsequently, GSEA enticement analysis suggested that five signalling pathways (e.g. cytokine–cytokine receptor interaction, IL‐17, JAK‐STAT, HIF‐1 and Insulin resistance) were significantly inhibited in both cell lines after silencing IL1RAP." (PMID 35488454, 2022).
laryngeal carcinoma (1 paper, 2019). Carcinoma that arises from the laryngeal epithelium. "The prognosis of laryngeal cancers could be improved by addition of markers such as IL1RAP, LANCL2, RYK, and SLC33A1." (PMID 31310629, 2019).
liver cancer (1 paper, 2022). An epithelial or non-epithelial malignant neoplasm that arises from the liver. "Myeloid malignancies with elevated IL1RAP and CCR6+ cancers that respond to CCL20 such as liver cancer might be first candidates." (PMID 36107259, 2022).
liver inflammatory diseases (1 paper, 2021). "Moreover, IL1RAP and TOLLIP, involved in cytokine–cytokine interaction and Toll-like receptor signaling pathways, have been reported to play a key role in liver inflammatory diseases." (PMID 34829865, 2021).
lymphoma (1 paper, 2022). A malignant (clonal) proliferation of B- lymphocytes or T- lymphocytes which involves the lymph nodes, bone marrow and/or extranodal sites. "Using flow cytometry, we found that knockdown of either gene significantly induced PEL cell apoptosis, which was further confirmed by the increased cleavage of PARP, Caspases-3 and -9, these major apoptosis markers from IL1R1 or IL1RAP knockdown lymphoma cells." (PMID 36457850, 2022).